WDR83 (WD repeat domain 83)
Description:
Molecular scaffold protein for various multimeric protein complexes. Acts as a module in the assembly of a multicomponent scaffold for the ERK pathway, linking ERK responses to specific agonists. At low concentrations it enhances ERK activation, whereas high concentrations lead to the inhibition of ERK activation. Also involved in response to hypoxia by acting as a negative regulator of HIF1A/HIF-1-alpha via its interaction with EGLN3/PHD3. May promote degradation of HIF1A. May act by recruiting signaling complexes to a specific upstream activator (By similarity). May also be involved in pre-mRNA splicing. Participates in tight junction development by regulating apico-basal polarity, a key step in tissue development and organization. Mechanistically, regulates the translocation of PAR6-aPKC from the cytoplasm to the apical surface by acting as an adapter between PARD6B AND CRB3. Also acts as a negative regulator of mTORC1 under nutrient-rich conditions by binding to the active Rag GTPases to inhibit mTORC1 localization to the lysosome and phosphorylation of downstream targets. This facilitates constitutive basal autophagy during nutrient availability.
Synonyms: MORG1
Tractability: PROTAC: ubiquitination databases record sites on it.
Gene: Protein-coding gene on chromosome 19 (12,666,802 to 12,675,832, forward strand). Ensembl gene ENSG00000123154.
Subcellular location: Cytoplasm; Lysosome; Nucleus
Subcellular location (Human Protein Atlas): Nucleoplasm; Vesicles; Basal body; Centriolar satellite; Cytosol
Pathways (Reactome):
Signal Transduction: MAP2K and MAPK activation
Gene Ontology:
Molecular function: protein binding
Biological process: mRNA splicing, via spliceosome; RNA splicing, via transesterification reactions
Cellular component: catalytic step 2 spliceosome; cytoplasm; lysosome; spliceosomal complex; endosome membrane; nucleus
Genetic constraint (gnomAD): Loss-of-function variants: 39 observed, 39.81 expected, observed/expected ratio (o/e) 0.98, 90% interval 0.76 to 1.28. The upper end of that interval is the gene's LOEUF score, 1.28, which puts it in group 5 of 6, group 1 being the genes least tolerant of losing a copy. Missense variants: 445 observed, 413.77 expected, observed/expected ratio (o/e) 1.08, 90% interval 0.99 to 1.16. Synonymous variants: 174 observed, 184.44 expected, observed/expected ratio (o/e) 0.94, 90% interval 0.83 to 1.07.
Homologues: Orthologues: chimpanzee WDR83 (99% identical), macaque WDR83 (98% identical), dog WDR83 (97% identical), pig WDR83 (95% identical), mouse Wdr83 (94% identical), rabbit WDR83 (94% identical), guinea pig WDR83 (94% identical), rat Wdr83 (93% identical), zebrafish wdr83 (72% identical), tropical clawed frog wdr83 (69% identical), Caenorhabditis elegans wdr-83 (46% identical), Drosophila melanogaster CG4935 (44% identical).
Diseases named in the same sentence as WDR83 in open-access papers:
WDR83 is named in the same sentence as 13 diseases in open-access papers, as found by Europe PMC text mining. Sharing a sentence is not in itself a finding about the gene and the disease. The quoted sentences say what the papers report.
lung carcinoma (1 paper, 2021). "As a pair of protein-coding cis-sense/antisense transcripts, WDR83 and DHPS are upregulated simultaneously and correlate positively in lung cancer." (PMID 35126467, 2021).
oral cavity tumors (1 paper, 2022). "Interestingly, three patients with oral cavity tumors (51.1, 207, and 339) presented gains encompassing WDR genes (WDR83, WDR19, and WDR47, respectively)." (PMID 36552033, 2022).
prostate carcinoma (1 paper, 2022). A carcinoma that arises from epithelial cells of the prostate gland. "The upregulation of WDR83 and WDR19 has been implicated in gastric and prostate cancers, respectively." (PMID 36552033, 2022).
cancer (1 paper, 2024). A tumor composed of atypical neoplastic, often pleomorphic cells that invade other tissues. "As a consequence of WDR83 depletion cell proliferation and migration increase and low levels of WDR83 mRNA are correlated with poor prognosis for several cancers." (PMID 38450633, 2024).
tumor (1 paper, 2021). "Other genes, TNPO2 and WDR83, were related to tumor development." (PMID 34645387, 2021).
WDR83 also shares sentences with these, for which no sentence is quoted: diabetes (2 papers); diabetic nephropathy (2); Anxiety (1); endotoxemia (1); gastric cancer (1); glioma (1); Sepsis (1); type 2 diabetes mellitus (1).